TTYH2 (tweety family member 2)
Description:
Calcium-independent, swelling-dependent volume-regulated anion channel (VRAC-swell) which plays a pivotal role in the process of regulatory volume decrease (RVD) in the brain through the efflux of anions like chloride and organic osmolytes like glutamate (By similarity). Probable large-conductance Ca(2+)-activated chloride channel.
Synonyms: C17orf29
Tractability: Antibody: UniProt places it where antibodies can reach, with high confidence; its Gene Ontology location is reachable by antibodies, with high confidence; UniProt predicts a signal peptide or a membrane-spanning region. PROTAC: UniProt records ubiquitination sites on it.
Gene: Protein-coding gene on chromosome 17 (74,213,518 to 74,262,020, forward strand). Ensembl gene ENSG00000141540.
Subcellular location: Cell membrane
Pathways (Reactome):
Transport of small molecules: Stimuli-sensing channels
Gene Ontology:
Molecular function: chloride channel activity; protein binding; volume-sensitive anion channel activity; calcium ion binding; intracellularly calcium-gated chloride channel activity; volume-sensitive chloride channel activity
Biological process: chloride transmembrane transport; L-glutamate transmembrane transport
Cellular component: plasma membrane; membrane
Genetic constraint (gnomAD): Loss-of-function variants: 49 observed, 69.26 expected, observed/expected ratio (o/e) 0.71, 90% interval 0.56 to 0.9. The upper end of that interval is the gene's LOEUF score, 0.9, which puts it in group 3 of 6, group 1 being the genes least tolerant of losing a copy. Missense variants: 631 observed, 720.18 expected, observed/expected ratio (o/e) 0.88, 90% interval 0.82 to 0.94. Synonymous variants: 272 observed, 306.74 expected, observed/expected ratio (o/e) 0.89, 90% interval 0.8 to 0.98.
Homologues: Orthologues: chimpanzee TTYH2 (99% identical), macaque TTYH2 (93% identical), dog TTYH2 (88% identical), pig TTYH2 (86% identical), guinea pig TTYH2 (83% identical), mouse Ttyh2 (83% identical), rat Ttyh2 (83% identical), rabbit TTYH2 (76% identical), tropical clawed frog ttyh2 (68% identical), zebrafish ttyh2 (66% identical), zebrafish ttyh2l (61% identical), Drosophila melanogaster tty (28% identical), and 2 more. Paralogues in human: TTYH3 (40% identical), TTYH1 (35% identical).
Diseases named in the same sentence as TTYH2 in open-access papers:
TTYH2 is named in the same sentence as 30 diseases in open-access papers, as found by Europe PMC text mining. Sharing a sentence is not in itself a finding about the gene and the disease. The quoted sentences say what the papers report.
colon cancer (4 papers, 2019 to 2022). "TTYH2 has been studied in association with colon cancer through gene expression, functional gene knockdowns, and binding assays." (PMID 34262434, 2021). "In contrast with the functional studies conducted on TTYH2 in colon cancer, TTYH1 and TTYH3 have only been studied in colon cancer through gene expression assays." (PMID 34262434, 2021). "Similar to gliomas, differential TTYH2 expression patterns between pathological and normal cells and tissue are seemingly cell and tissue type-dependent in colon cancer." (PMID 34262434, 2021). "Silence of TTYH2 by transfecting siRNA markedly inhibited proliferation and migration of colon cancer cells." (PMID 34729116, 2021). "The studies attempting to characterize TTYH2 in colon cancer consistently suggest TTYH2 facilitates tumor growth and/or metastasis." (PMID 34262434, 2021). "RT-PCR found TTYH2 upregulation in colon cancer cell lines (Caco-2, LoVo, and DLD-1) and human colon cancer tissue, although RNA-Seq of human blood platelets from colorectal cancer patients showed TTYH2 downregulation." (PMID 34262434, 2021). "Additionally, siRNA knockdown of TTYH2 in colon cancer-derived cell lines Caco-2 and DLD-1 showed increased cell aggregation and impaired cell proliferation, suggesting a role of TTYH2 in tumor growth and metastasis." (PMID 34262434, 2021). "In addition, TTYH1 and TTYH2 are upregulated in glioblastoma cells and colon cancer cells, respectively." (PMID 31181821, 2019).
osteosarcoma (4 papers, 2020 to 2022). A usually aggressive malignant bone-forming mesenchymal neoplasm, predominantly affecting adolescents and young adults. "Additionally, an siRNA knockdown of TTYH2 performed on osteosarcoma cell line U2OS (which showed high TTYH2 expression) attempted to identify possible associations between TTYH2 expression and cancerous properties of U2OS cells." (PMID 34262434, 2021). "On the basis of our previous and current studies, we believe that TTYH1 and TTYH2 can serve as potential therapeutic targets in osteosarcoma." (PMID 35455021, 2022). "In addition to breast cancer, TTYH2’s role has been investigated in osteosarcoma where RNA-Seq showed TTYH2 upregulation in mouse osteosarcoma samples." (PMID 34262434, 2021). "In contrast with TTYH2, TTYH1 and TTYH3 have only been studied in osteosarcoma through microarray and RNA-Seq experiments showing TTYH1 downregulation and TTYH3 upregulation." (PMID 34262434, 2021). "TTYH2, in turn, is a volume-regulated anion channel that regulates transcription factors involved in EMT and is critical for the migration of osteosarcoma cells." (PMID 32831131, 2020).
colorectal cancer (2 papers, 2019 to 2021). A primary or metastatic malignant neoplasm that affects the colon or rectum. "Among three human TTYH gene homologs that are the members of Ca2+-activated Cl- channel responsive family, only TTYH2 has been studied in renal cell carcinoma and colorectal cancer." (PMID 31652813, 2019).
gastric cancer (2 papers, 2021 to 2024). A primary or metastatic malignant neoplasm involving the stomach. "First, ICl,swell was not affected by shRNA-mediated knockdown of LRRC8A but, in contrast, was largely abolished by double knockout of TTYH1 and TTYH2 in gastric cancer SNU-601 cells." (PMID 38238667, 2024).
glioblastoma (2 papers, 2019 to 2021). The most malignant astrocytic tumor (WHO grade IV). "For example, TTYH1 and TTYH2 were upregulated in infiltrating compared to core neoplastic cells in glioblastoma patients." (PMID 34262434, 2021). "Furthermore, glioblastomas with 1p/19q chromosome arms codeletions (associated with diminished glioma propagation and impaired tumor microtube formation and function) show TTYH1 and TTYH2 downregulation and TTYH3 upregulation compared to 1p/19q non-codeleted gliomas." (PMID 34262434, 2021).
renal cell carcinoma (2 papers, 2019 to 2021). "In addition, the upregulation of TTYH2 expression was detected in renal cell cancer, suggesting that its upregulation might play an oncogenic role in renal tumorigenesis." (PMID 34729116, 2021).
ataxia telangiectasia (1 paper, 2021). Ataxia-telangiectasia is the association of severe combined immunodeficiency (affecting mainly the humoral immune response) with progressive cerebellar ataxia. "Additional RNA-Seq and microarray experiments have demonstrated TTYH3 downregulation in ataxia-telangiectasia, TTYH2 upregulation in cerebral small vessel disease, and TTYH2 downregulation in pick disease and progressive supranuclear palsy." (PMID 34262434, 2021).
atypical teratoid rhabdoid tumor (1 paper, 2021). Atypical teratoid rhabdoid tumor (ATRT) is a highly malignant central nervous system (CNS) rhabdoid tumor (RT) found almost exclusively in children. "Other microarrays demonstrate TTYH1 and TTYH2 downregulation in subependymal giant cell astrocytoma samples as well as TTYH2 downregulation and TTYH3 upregulation in atypical teratoid rhabdoid tumors." (PMID 34262434, 2021).
breast carcinoma (1 paper, 2021). "In contrast with TTYH1, TTYH2 and TTYH3 have only been studied in breast cancer through RNA-Seq and microarray analyses with TTYH2 showing downregulation and TTYH3 showing upregulation in breast cancer-associated cells and tissues." (PMID 34262434, 2021).
colon adenocarcinoma (1 paper, 2024). "TTYH2 has also been described to promote cancer cell colony formation, thereby supporting tumour growth and metastasis in colon adenocarcinoma." (PMID 38902676, 2024).
COVID-19 (1 paper, 2024). A disease caused by infection with severe acute respiratory syndrome coronavirus 2. "Thus, the unbalanced expression levels of TTYH2 were one of the reasons for concomitant epilepsy in patients with COVID-19." (PMID 38300446, 2024).
epilepsy (1 paper, 2024). A brain disorder characterized by episodes of abnormally increased neuronal discharge resulting in transient episodes of sensory or motor neurological dysfunction, or psychic dysfunction. "Moreover, there are 23 cell subtypes identified through the scRNA-seq transcriptomics data of epilepsy, and SARS-CoV-2 receptor TTYH2 was found to be specifically expressed in oligodendrocyte and astrocyte cell subtypes." (PMID 38300446, 2024).
hepatocellular carcinoma (1 paper, 2024). A malignant tumor that arises from hepatocytes. "Additionally, TTYH2 and AP1M2 are implicated in cancer progression through regulation of the JNK/ERK Signalling Pathway in Hepatocellular Carcinoma." (PMID 38902676, 2024).
cancer (6 papers, 2019 to 2024). A tumor composed of atypical neoplastic, often pleomorphic cells that invade other tissues. "Based on the gene expression profiles of these three types of cells (VRAC-active, VRAC-deficient, and VRAC-restored), we selected two candidate VRAC genes, TTYH1 and TTYH2, and confirmed that the channels they encode can act as VRACs in several types of cancer cells." (PMID 31181821, 2019). "Therefore, it is worth investigating whether gene deficiency of TTYH1 or TTYH2 is associated with the cisplatin resistance in these cancer cells." (PMID 31181821, 2019). "A fourth study attributed endogenous anionic currents in SNU-601, HepG2, and LoVo cancer cells to TTYH2 and/or TTYH1 channel activity." (PMID 34824283, 2021). "Recently, the TTYH1 and TTYH2 subunits have been identified as novel components of VRAC in some cancer cells." (PMID 35054564, 2021). "To establish the VRAC activity of TTYH1 and TTYH2, we investigated other cancer cell lines that endogenously express these two channels." (PMID 31181821, 2019). "TTYH2 expression is significantly upregulated in the tumors of these cancers and is involved in their proliferation in vitro." (PMID 31652813, 2019). "Taken together, these results suggest that TTYH1 and TTYH2 function independently as VRACs in various cancer cells." (PMID 31181821, 2019). "Although leucine-rich repeat–containing 8A (LRRC8A) has been characterized as a molecular component of VRACs, here we show that Drosophila melanogaster tweety homologue 1 and 2 (TTYH1 and TTYH2) are critical for VRAC currents in cancer cells." (PMID 31181821, 2019). "A caveat when comparing pathological to normal tissues and cells is that RNA-Seq and microarray experiments demonstrate how TTYH1 and TTYH2 expression patterns and cancers may be cell and tissue-type-dependent." (PMID 34262434, 2021). "We found that TTYH1 or TTYH2 could act as VRACs in cancer cells (SNU-601, HepG2, and LoVo cells), and that these channels were not expressed in MCF-7 cells." (PMID 31181821, 2019). "These binding partners of TTYH1 or TTYH2 may be involved in the regulatory mechanisms of VRACs in diverse normal tissues and cancer cells." (PMID 31181821, 2019). "Therefore, the functional roles of TTYH1- or TTYH2-mediated VRAC currents should be examined in these cancer cells." (PMID 31181821, 2019). "TTYH2 is the second member of the TTYHs family which was overexpressed in cancers." (PMID 31652813, 2019). "However, little is known about the expression and function of the TTYHs in any cancer, although the expression of TTYH2 was reported to be involved in cell proliferation and aggregation in colon carcinoma and in the invasion and migration of osteosarcoma cells." (PMID 31652813, 2019). "In these cancer cells, TTYH1 and TTYH2 regulate cell proliferation and migration, which can be effectively inhibited by silencing the corresponding gene." (PMID 31181821, 2019). "Taken together, our data clearly show that TTYH1 and TTYH2 can act as LRRC8A-independent VRACs, suggesting novel therapeutic approaches for VRACs in cancer cells." (PMID 31181821, 2019). "In addition, we examined the expression of TTYH1 or TTYH2 in several cancer cell lines and found that VRAC currents of these cells were abolished by gene silencing of TTYH1 or TTYH2." (PMID 31181821, 2019).
cardiovascular disease (1 paper, 2016). "TTYH2 and NEDD8 may play a role in the genetic architecture of cardiovascular disease, blood pressure regulation, and other disorders." (PMID 26752167, 2016).
TTYH2 also shares sentences with these, for which no sentence is quoted: tumor (3 papers); brain cancer (1); brain glioma (1); central nervous system demyelinating disease (1); cerebral small vessel disease (1); giant cell astrocytoma (1); glioma (1); lymph node metastasis (1); multiple sclerosis (1); multisystem atrophy (1); Parkinson disease (1); Pick disease (1); progressive supranuclear palsy (1); sarcoma (1); Streptococcus pneumoniae infection (1).